MTOR (mechanistic target of rapamycin kinase)
Diseases named in the same sentence as MTOR in open-access papers (continued):
Sharing a sentence is not in itself a finding about the gene and the disease.
tumor (continued). "We also found rapamycin (mTOR inhibitor) suppressed tumor sphere in Huh7 cells." (PMID 24721996, 2014). "The deregulation of mTOR activity found in the tumours of BHD animal models could be due to mTOR's general involvement in cancerous growth rather than a direct effect of FLCN's absence." (PMID 24910976, 2014). "Consequently, mTOR inhibition affected NK cell cytotoxic responses toward target tumor YAC-1 cells and resulted in elevated viral loads in the infected organs." (PMID 24795729, 2014). "Treatment with γ-tocotrienol also inhibited the activation of AKT, mTOR, and P70S6K kinases in a time-dependent manner in HCCLM3 cells, suggesting that the AKT/mTOR pathway may mediate both anti-angiogenic/anti-tumor effects of γ-tocotrienol." (PMID 24722367, 2014). "It is known that PMA, a classic tumor-promoter, activates mTOR and MAPK pathways." (PMID 25587030, 2014). "Combined use of an HDAC- and mTOR inhibitor might then diminish pro-tumour effects triggered by the HDAC- (Akt/mTORhigh) or mTOR inhibitor (aH3/aH4low) alone." (PMID 24779401, 2014). "KRAS PTEN tumours are uniquely responsive to mTOR inhibition." (PMID 24717934, 2014). "It is possible that inhibition of the JAK/STAT pathway could indirectly influence the activation of mTOR, thereby suppressing tumor growth." (PMID 25149535, 2014). "Consistent with the results of the present study, NMI tumours may extend and upregulate mTOR expression up to the basal urothelial layer, which is concordant with an enhanced malignant potential that will guide growth and progression of the primary tumour." (PMID 25202348, 2014). "The tumor suppressor sMEK1 functionally regulates apoptosis through mTOR regulation." (PMID 25153728, 2014). "Activating mutations in the mTOR gene have been identified in a small number of malignancies, although these have not been clearly associated with tumour development." (PMID 25202348, 2014). "PTEN functions as a tumor suppressor by negatively regulating the Akt/PI3K signaling pathway, which is overactive if PTEN is faulty or deficient, thus reducing apoptosis and allowing proliferation by induction of mTOR." (PMID 24731550, 2014). "In addition, the mTOR pathway is a critical part of the cellular circuitry which is often constitutively activated in tumor cells." (PMID 24800261, 2014). "Tumor progression and resistance development in RCC in vitro and in vivo towards different agents has been associated with increased activity of the PI3K/Akt/mTOR signaling pathway." (PMID 24935000, 2014). "The PI3K/AKT/mTOR pathway regulates cell proliferation and tumor growth." (PMID 25119929, 2014). "Increased mTOR activity, as well as increased levels of phosphorylation of its downstream targets, eukaryotic translation initiation factor 4E binding protein 1 and ribosomal protein S6 kinase, have been detected in a significant percentage of human tumours." (PMID 25202348, 2014). "Of note, the patient with the highest TTF while on an mTOR-based regimen had a tumor that did not harbor KRAS mutations." (PMID 24586741, 2014). "In this study, we show that the combination of a selective MEK inhibitor and a PI3K/mTOR inhibitor is effective against tumor cell lines refractory to gefitinib by three different mechanisms: an EGFR gatekeeper T790M mutation, MET amplification, and KRAS/PIK3CA mutation." (PMID 24939055, 2014). "Many human tumor suppressors negatively regulate mTOR signaling." (PMID 25257528, 2014). "In vitro study, we also observed whether α-Solanine intervened in the Wnt/β-catenin, Akt/mTOR, Stat3 and NF-κB pathways which had a critical influence on tumor cells proliferation, angiogenesis and metastasis." (PMID 24505326, 2014). "Furthermore, our data suggest that mTOR inhibitors can suppress autocrine and paracrine growth stimulation of tumor and lymphatic endothelial cells by impairing VEGF-C/VEGFR-3 axis and release of soluble VEGFR-2." (PMID 23815869, 2013).
tumor (continued). "In this study, we attempted to capitalize on in vitro data suggesting that mTOR inhibition could enhance tumor cell killing by DNA damaging agents such as irinotecan through the HIF-1α pathway." (PMID 24216984, 2013). "However, the relationship among BCAAs, the mTOR signalling pathway, cellular senescence, and tumor suppression has been unclear." (PMID 24223226, 2013). "Furthermore, metformin treatment also markedly reduced the expression of cyclin D1 and p-mTOR, which was confirmed by the scoring of percentage positive cells under 400× magnification in ten randomly selected areas in each tumor sample." (PMID 24351837, 2013). "Our results confirm that the inhibition of VEGF translation induced by mTOR inhibitors participates in the observed tumor cell apoptosis and antitumor response in vivo and underscore the importance of IRES-mediated VEGF translation as a possible resistance mechanism to rapalogs." (PMID 23533410, 2013). "As the mTOR pathway is normally involved in stimulation of cell growth and proliferation, mutation of one of the TSC genes leads to disinhibition of the mTOR pathway, which promotes excessive cell growth and tumor formation in TSC." (PMID 23437388, 2013). "In contrast, the PI3K/Akt/mTOR pathway is constitutively activated by the expression of p-Akt (Ser 473), almost exclusively in the nuclear compartment of the tumor cells and of p-mTOR phosphorylated on Ser 2448, also with variable mild to moderate nuclear expression." (PMID 23922674, 2013). "Severe combined immunodeficient mice injected with IBC cells treated with Reishi for 13 weeks show reduced tumor growth and weight by ∼50%, and Reishi treated tumors showed reduced expression of E-cadherin, mTOR, eIF4G, and p70S6K, and activity of extracellular regulated kinase (ERK1/2)." (PMID 23468988, 2013). "Perinuclear localization of RIG1 has been shown to inhibit expression or activation of signaling molecules such as HER2, RAS, PI3K/AKT, mTOR, and type I transglutaminase that are involved in the regulation of cell growth, apoptosis, tumor invasion, and cell differentiation." (PMID 23687991, 2013). "Furthermore, in engrafted anaplastic large-cell lymphoma (ALCL) mouse models, miR-101 binds directly to the 3′-UTR of mTOR and leads to reduced tumour growth." (PMID 23434669, 2013). "mTOR inhibitors enhanced radiation damage of tumor vasculature." (PMID 24403259, 2013). "A potential mechanism by which upregulation of these miRNAs may exert an anti-tumor effect involves the influence of miR-125b and miR-100 over the Akt/mTOR pathway." (PMID 24047116, 2013). "The combination of an inhibitor of RAS/PI3K/PTEN/AKT/mTOR signaling with sorafenib might thus be expected to be more effective for inhibition of tumor growth than sorafenib alone." (PMID 23342156, 2013). "Furthermore, it has been firmly established that constitutive activation of the PI3K/AKT/mTOR signalling pathway is a determinant of tumour cell growth and survival in many different solid tumours." (PMID 24376606, 2013). "The activation of mTOR pathway by BRAF is consistent with our previous studies on human tumours." (PMID 23904987, 2013). "To prove the role of VEGF inhibition in the cytotoxic effects of mTOR inhibition, we generated isogenic HS Sultan tumor cell lines that expressed a VEGF transgene regulated by the potent p27 IRES sequence, thereby allowing us to express ectopic VEGF using the cap-independent salvage pathway." (PMID 23533410, 2013). "Further investigation of the association between autophagy activation and the anti-tumor effects of mTOR inhibitors may unveil new strategies for tumor therapy." (PMID 24179542, 2013). "Thus, we initiated the current study to definitively ask if altered VEGF expression and downregulation of angiogenesis were the key effects of mTOR inhibitors that mediated tumor cell apoptosis and tumor rejection in vivo." (PMID 23533410, 2013).
tumor (continued). "AKT is an integral part of a pivotal signaling pathway, which promotes tumor cell proliferation and protects cells from apoptosis and senescence via a variety of downstream pathways, such as mammalian target of rapamycin (mTOR), glycogen synthase kinase 3 (GSK-3) and Forkhead box O (FOXO)." (PMID 24265816, 2013). "Thus, the coordinate inhibition of mTOR and autophagy by treatment with CCI-779 and HCQ reduced tumor volume in vivo that was associated with apoptosis." (PMID 23383069, 2013). "When published data are taken into consideration, it is apparent that increased cytosolic calcium could inhibit mTOR to induce autophagy in human tumor cell lines and this pathway is mediated by Ca2+/calmodulin-dependent kinase kinase-β (CaMKK-β) and AMPK." (PMID 23847620, 2013). "This indicates a differential response in the normal tissue compared to the tumor tissue and might be a mechanism of resistance to mTOR inhibition in this setting." (PMID 23593290, 2013). "Most investigations in bulk tumor cells support a simplified working model in which metformin exerts anti-tumoral effects by indirectly activating AMPK followed by subsequent suppression of mTOR." (PMID 24204632, 2013). "Indeed, accelerated tumor growth upon constitutive activation of AKT is reversed by inhibition of mTOR." (PMID 23638184, 2013). "However, our laboratory identified synergistic anti-tumor activity in vitro with combination mTOR inhibition and VEGF blockade." (PMID 24047116, 2013). "In addition, AZD8055 apparently blocked radiation-stimulated mTOR expression and phosphorylation in tumor tissues." (PMID 23886294, 2013). "We next tested whether ectopic VEGF expressed from the p27IRES-VEGF construct could rescue tumor cells from the antitumor effects of mTOR inhibitors in vivo." (PMID 23533410, 2013). "Akt-inhibitor-resistant tumours displaying elevated SGK1 might be better treated with mTOR inhibitors that suppress SGK1 activity." (PMID 23581296, 2013). "mTOR inhibitors reduce tumor progression and growth through SREBP-1." (PMID 24403259, 2013). "To test this hypothesis, we assessed the effects on tumor growth and the levels of phosphorylated mTOR and p70 S6K in mice treated with diet alone versus diet in combination with everolimus treatment." (PMID 24353195, 2013). "The activation of autophagy by the inhibition of the mammalian target of rapamycin (mTOR) may contribute to anti-tumor actions." (PMID 24179542, 2013). "Next, we tested 64Cu-NOTA-bevacizumab as an mTOR inhibition tumor response indicator." (PMID 23516584, 2013). "Insulin, angiotensin-II and epidermal growth factor have been shown to up-regulate HIF in the presence of molecular oxygen and mTOR inhibition decreases tumour progression partially to decreased neo-vascularisation, indicating mTOR as a regulator of HIF by increasing its mRNA translation." (PMID 23758895, 2013). "Accumulating evidence indicates a pivot role of Akt/mTOR pathway in regulating CD4 + Foxp3+ regulatory T cells in tumor microenvironment.Therefore, targeting mTOR by rapamycin may be a promising therapeutic strategy for ASCC." (PMID 24124460, 2013). "Endothelial cells are more sensitive to mTOR inhibitors than tumor cells." (PMID 24403259, 2013). "Thus, inhibition of mTOR kinase activity impacts multiple pathways that are important for tumor maintenance such as the protein translation of several oncogenes." (PMID 24216984, 2013). "Finally, we explored the links between mTOR signaling and tumor cell autophagy that are altered by eATP." (PMID 23565201, 2013). "The Ras/Raf/ERK pathway provides a bypass for the mTOR pathway and, therefore, may result in tumor resistance." (PMID 23922674, 2013). "This suggests a role for novobiocin in the mTOR signaling pathway and indicates a novel molecular mechanism for novobiocin which may lead to new tumor drugs." (PMID 23671581, 2013).
tumor (continued). "Two signaling pathways, namely Raf/MEK/ERK and phosphatidylinositol 3-kinase (PI3K)/Akt/mammalian target of Rapamycin (mTOR) pathways, play central roles in many types of tumor cell proliferation, and can lead to aberrant signaling and uncontrolled proliferative diseases." (PMID 24133625, 2013). "Moreover, since HGF confers resistance to targeted drugs in several tumor types, clinical trials of mTOR inhibitors are warranted." (PMID 23690929, 2013). "The mTOR pathway promotes tumor growth and survival, while suppressing autophagy." (PMID 23818925, 2013). "T cell ITH was higher in tumours pretreated with an mTOR inhibitor, which could suggest that therapy can influence adaptive tumour immunity." (PMID 24122851, 2013). "By contrast, decreased expression levels were found for mTOR- and tumor progression-related genes." (PMID 23587162, 2013). "In the patient with DSRCT the PI3K/Akt/mTOR pathway is constitutively activated by virtue of the expression of p-Akt (Ser 473) in the nuclear compartment of the tumor cells, and p-mTOR phosphorylated on Ser 2448, suggesting mTORC2 (rictor+mTOR) as the dominant form." (PMID 23922674, 2013). "In preclinical models, SGK1 knockout mice had increased response to tumor immunotherapy compared to mice with functional SGK1, suggesting that mTOR up-regulation dampens or inhibits anti-tumor immunity (unpublished data from Dr. Jonathan D. Powell, Johns Hopkins University)." (PMID 24829749, 2013). "As proliferation of tumors is related to AKT/mTOR activation and signaling and can be inhibited by rapamycin-derivatives, we specifically evaluated the effects of candidate peptides on this pathway as well as on tumor cell proliferation." (PMID 24260544, 2013). "One perplexing question is therefore whether mTOR inhibition increases immunity to viruses, bacteria and tumours, while at the same time protects organ transplants from rejection." (PMID 24565200, 2013). "To determine whether tumor type had an influence in the RR of FAEs with mTOR inhibitors, we performed a subgroup analysis according to tumor types." (PMID 23785409, 2013). "4E-BP1 plays a critical role in mediating tumor proliferation and progression in the mTOR pathway." (PMID 24403259, 2013). "Meanwhile, it could be speculated that activation of p-Akt caused activation of the PI3K/Akt/mTOR pathway, which provided a bypass for the Ras/Raf/ERK pathway and resulted in subsequent tumor growth." (PMID 23922674, 2013). "Phosphorylation of mTOR (p-mTOR) was evaluated in 167 resected OSCC tumours and 5 OSCC cell lines." (PMID 22333597, 2012). "The addition of an inhibitor of PI3K/mTOR to the standard androgen ablation treatment of advanced PCa may therefore be beneficial to patients with PTEN deleted tumor." (PMID 23171135, 2012). "Single agent blockade of either the AR or mTOR pathway showed comparable levels of tumor response; however the combination treatment regimen (based on the clinical dosing schedules for each) resulted in virtually complete inhibition of tumor growth." (PMID 22614157, 2012). "In conclusion, c-erb-B2, EGFR, mTOR, and ERCC1 overexpression and p27 loss may play roles in hepatocarcinogenesis and may be significant predictors of aggressive tumor behavior." (PMID 23162604, 2012). "However, SCF has different F-box substrate recognition modules for both tumor suppressors, such as p27, p57, and p21 and oncogenes, such as Cyclin D1, mTOR, and c-Myc." (PMID 23029392, 2012).
tumor (continued). "The COX-independent pathways which have been shown to be altered by high concentrations of aspirin involve: i) the inhibition of pro-tumoral signalings (such as Wnt/β-catenin, ERK, NF-kb and mTOR); and ii) the activation of anti-tumor signaling (such as AMPK pathway)." (PMID 24281340, 2012). "As a single agent, the mTOR inhibitor everolimus did not cause tumor regression but induced a significant inhibition of tumor growth." (PMID 22761648, 2012). "In sporadic MTC without RET mutations, over 50% of tumor samples show activation of AKT or mTOR by immunohistochemistry." (PMID 23077520, 2012). "Xenograft experiments revealed that tumor cells overexpressing GOLPH3 have an increased sensitivity to the mTORC1 inhibitor, rapamycin, and GOLPH3-dependent oncogenesis is associated with increased mTOR signaling." (PMID 22905766, 2012). "Indeed, a recent report demonstrates that cytokines secreted by a small number of vGPCR-positive tumor cells activate signaling pathways in neighboring cells, converging on mTOR-dependent VEGF up-regulation." (PMID 23316192, 2012). "The clinical context for interpreting the present findings from immunohistochemical examination of rat and human tumours is that phosphorylated S6 ribosomal protein is a marker indicating activity of the mammalian target of the anti-tumour drug rapamycin (mTOR) in cell proliferation." (PMID 23105973, 2012). "In fact the PI3K/AKT/mTOR pathway may be required for at least some of the tumor-promoting effects of AXL." (PMID 23077658, 2012). "However, irradiated tumours had reduced phosphorylation of Akt, mTOR and it‘s target translation initiation inhibitor 4EBP1." (PMID 22607554, 2012). "Even though the mTOR kinase itself does not seem to be a direct target of any viral protein, all the known human tumor viruses appear to interfere with PI3K-AKT-mTOR signaling, most likely to exploit the growth- and survival promoting function of these pathways." (PMID 24710474, 2012). "PTEN is the critical tumor suppressor of the PI3K/Akt/mTOR signaling pathway." (PMID 26097796, 2012). "Activation of PI3K/AKT pathway signaling leads to the mTOR-mediated tumor angiogenesis." (PMID 23344184, 2012). "Since vascular normalization improves tumor oxygenation as well as delivery of therapeutic drugs, examining whether such a process occurs in the case of mTOR inhibitors may explain the efficacy of rapamycin's radiosensitizing effects." (PMID 23185335, 2012). "Thus, this study suggests that Tir8/Sigirr is a tumor suppressor that controls colonic tumorigenesis by inhibiting IL-1- and TLRs-induced mTOR-mediated cell cycle progression and consequent genetic instability." (PMID 23112799, 2012). "PI3K/Akt/mTOR signaling thus confers a selective survival advantage on tumor cells." (PMID 22481932, 2012). "Large quantity of supposition had been proposed to provide biologic mechanisms by which the PTEN/AKT/mTOR axis could promote the evolution and metastasis of tumor." (PMID 22815832, 2012). "This enlargement of tumor following cessation of therapy might be due to normalization of cell size and resumption of cell proliferation, as mTOR and its downstream proteins S6 Kinase 1 and 4E-BP1 play pivotal roles in this respect." (PMID 23077520, 2012). "Here, we examined whether the PI3K/mTOR (both mTORC1 and mTORC2) inhibitors BEZ235 and NVP-BGT226 (BGT226) could sensitise tumor cells with EGFR overexpression or Ras mutation to radiation." (PMID 22452803, 2012). "Taken together, we conclude that the tumor suppressive role of miR-99a may be mediated partially through mTOR pathway regulation." (PMID 23173671, 2012). "First, PI3K/mTOR inhibition by BEZ235 alone can result in alterations in tumor blood vessel morphology andfunctionality but this appears to be a dose-dependent effect and can affect the efficacy of radiotherapy significantly, as recently demonstrated by our group." (PMID 22452803, 2012).